ITPKA (inositol-trisphosphate 3-kinase A)
Description:
Catalyzes the phosphorylation of 1D-myo-inositol 1,4,5-trisphosphate (InsP3) into 1D-myo-inositol 1,3,4,5-tetrakisphosphate and participates to the regulation of calcium homeostasis.
Synonyms: IP3KA; IP3-3KA
Tractability: Small molecule: a structure with a bound ligand is known; it has a binding pocket of medium quality. Antibody: the Human Protein Atlas places it where antibodies can reach. PROTAC: its protein half-life has been measured.
Target class: Enzyme
Gene: Protein-coding gene on chromosome 15 (41,493,360 to 41,503,554, forward strand). Ensembl gene ENSG00000137825.
Subcellular location: Cytoplasm, cytoskeleton
Pathways (Reactome):
Metabolism: Synthesis of IP3 and IP4 in the cytosol
Gene Ontology:
Molecular function: inositol-1,4,5-trisphosphate 3-kinase activity; inositol hexakisphosphate kinase activity; calcium/calmodulin-dependent protein kinase activity; kinase activity; small GTPase binding
Biological process: cellular response to calcium ion; phosphatidylinositol phosphate biosynthetic process; response to calcium ion; inositol phosphate metabolic process; signal transduction; inositol phosphate biosynthetic process; modification of postsynaptic actin cytoskeleton
Cellular component: cytoskeleton; cytoplasm; cytosol; dendritic spine; glutamatergic synapse; postsynaptic actin cytoskeleton
Genetic constraint (gnomAD): Loss-of-function variants: 14 observed, 30.24 expected, observed/expected ratio (o/e) 0.46, 90% interval 0.31 to 0.72. The upper end of that interval is the gene's LOEUF score, 0.72, which puts it in group 2 of 6, group 1 being the genes least tolerant of losing a copy. Missense variants: 482 observed, 532.65 expected, observed/expected ratio (o/e) 0.9, 90% interval 0.84 to 0.98. Synonymous variants: 288 observed, 241.98 expected, observed/expected ratio (o/e) 1.19, 90% interval 1.08 to 1.31.
Homologues: Orthologues: chimpanzee ITPKA (100% identical), macaque ITPKA (99% identical), dog ITPKA (95% identical), rat Itpka (93% identical), mouse Itpka (93% identical), pig ITPKA (83% identical), guinea pig ITPKA (68% identical), rabbit ITPKA (65% identical), tropical clawed frog itpka (59% identical), zebrafish itpka (48% identical), Caenorhabditis elegans lfe-2 (30% identical), Drosophila melanogaster IP3K1 (28% identical), and 2 more. Paralogues in human: ITPKB (52% identical), ITPKC (46% identical), IPMK (16% identical), IP6K1 (15% identical), IP6K2 (14% identical), IP6K3 (14% identical).
Diseases named in the same sentence as ITPKA in open-access papers:
ITPKA is named in the same sentence as 31 diseases in open-access papers, as found by Europe PMC text mining. Sharing a sentence is not in itself a finding about the gene and the disease. The quoted sentences say what the papers report.
lung adenocarcinoma (6 papers, 2018 to 2023). A carcinoma that arises from the lung and is characterized by the presence of malignant glandular epithelial cells. "Besides its demonstrated association with carcinoma prognosis, ITPKA promotes cancer cell growth, invasion, and migration in renal cell carcinoma and lung adenocarcinoma." (PMID 36685893, 2022). "TFAP2A is the upstream transcription factor of ITPKA, which promotes the occurrence and development of lung adenocarcinoma (LUAD) by interacting with Drebrin1." (PMID 37208656, 2023). "Here we report that ITPKA is overexpressed in lung adenocarcinoma (LUAD) and positively correlated with advanced clinical parameters." (PMID 32015686, 2020). "In summary, the ITPKA has impacts on lung adenocarcinoma cell proliferation, migration, and cell death." (PMID 32015686, 2020). "Studies have shown that transcription factor AP-2 alpha (TFAP2α) promotes the proliferation, invasion, and metastasis of lung adenocarcinoma cells through ITPKA overexpression, which is induced by an interaction with Drebrin 1 (associated with cancer metastasis) and activation of EMT." (PMID 33988228, 2021). "Overall, this study presents distinct transcriptomic differences between lung adenocarcinoma growth patterns, which could be validated for the solid-expressed ITPKA and the lepidic-expressed angiogenin proteins." (PMID 30352093, 2018).
lung carcinoma (6 papers, 2020 to 2023). "ITPKA serves as an early diagnostic marker in lung cancer, whose overexpression promotes tumorigenesis." (PMID 31992202, 2020). "For this purpose, a dominant negative ITPKA mutant (ITPKAL34P) was overexpressed in H1299 lung cancer cells to inhibit the actin bundling activity of endogenous ITPKA." (PMID 36688944, 2023). "In summary, inhibition of the actin bundling activity of ITPKA reduced actin dynamics in filopodia and decreased the migratory potential of H1299 lung cancer cells." (PMID 36688944, 2023). "In summary, our data show that in H1299 lung cancer cells mainly the actin bundling activity of ITPKA promotes migration and invasion, which is slightly enhanced by its InsP3-kinase activity after cellular stimulation with ATP." (PMID 36688944, 2023). "In particular, in lung cancer cells this up-regulation is associated with bad prognosis and it has been shown that a high level of ITPKA increases migration and invasion of lung cancer cell lines." (PMID 36688944, 2023). "To address this issue, we inhibited endogenous actin bundling activity of ITPKA in lung cancer H1299 cells by overexpressing the dominant negative mutant ITPKAL34P." (PMID 36688944, 2023). "In former studies, we revealed that a high level of ITPKA increased trans-migration of different types of tumor cells and demonstrated that overexpression of ITPKA in H1299 lung cancer cells significantly increased metastasis in SCID mice." (PMID 36688944, 2023). "In a former study we revealed that down-regulation of ITPKA in lung cancer H1299 cells decreased trans-migration." (PMID 36688944, 2023). "The biological functions of ITPKA in lung cancer and breast cancer have attracted considerable attention." (PMID 33879633, 2021). "In the present study, we confirmed the relevance of ITPKA for metastasis by down-regulating endogenous ITPKA in H1299 cells, and thus validated that both up- and down-regulation of ITPKA control dissemination of lung cancer cells in vivo." (PMID 36688944, 2023). "The latest research from Sabine’s team has demonstrated that in H1299 lung cancer cells, the mechanism by which ITPKA promoted migration and invasion was predominantly depending on the ability of binding to F-actin, which will induce cancer cells to form a tight flexible actin networks." (PMID 37664985, 2023). "Thus, depletion of ITPKA-expression reduces dissemination of lung cancer cells in vivo by 78%, showing that ITPKA is essential for dissemination of H1299 lung cancer cells." (PMID 36688944, 2023). "In conclusion, the data from Sabine’s team suggested that in H1299 lung cancer cells, the mechanism by which ITPKA promoted migration and invasion was predominantly depend on the ability of binding to F-actin, which induces cancer cells to form a tight flexible actin networks." (PMID 37664985, 2023). "However, the contribution of the inositol polyphosphate kinase ITPKA to lung cancer development remains unclear." (PMID 32015686, 2020).
glioma (4 papers, 2021 to 2026). A benign or malignant brain and spinal cord tumor that arises from glial cells (astrocytes, oligodendrocytes, ependymal cells). "In addition, inositol-trisphosphate 3-kinase A (ITPKA) was a significantly enriched differentially expressed gene associated with the inositol phosphate metabolism pathway in glioma cells." (PMID 33879633, 2021). "One such regulator is inositol‐trisphosphate 3‐kinase A (ITPKA), which is aberrantly overexpressed in glioma and correlates with poor patient prognosis." (PMID 41200384, 2025). "Functional studies have demonstrated that ITPKA promotes glioma cell proliferation and invasion, underscoring its role in tumor progression." (PMID 41200384, 2025).
liver cancer (2 papers, 2023 to 2025). An epithelial or non-epithelial malignant neoplasm that arises from the liver. "In addition, it has been suggested that IP3 kinase (ITPKA) expression is increased in liver cancer and associated with poorer patient prognosis and survival, pointing to liver cancer potentially showing an increase in IP4 content." (PMID 41032702, 2025). "In recent years, increasing evidence has shown that ITPKA is overexpressed and acts as a promoter in a variety of cancers, including breast, lung, and liver cancer." (PMID 37056339, 2023).
renal cell carcinoma (2 papers, 2022 to 2023). "ITPKA can promote the growth, migration and invasion of renal cell carcinoma (RCC) by activating the m-TORC1 signaling pathway." (PMID 37056339, 2023).
breast carcinoma (1 paper, 2022). "Upregulated ITPKA expression discovered in patients with breast cancer, it may serve as an independent prognostic marker in cancer of the breast." (PMID 36685893, 2022).
hepatocellular carcinoma (1 paper, 2015). A malignant tumor that arises from hepatocytes. "However, the expression and the prognostic value of ITPKA in hepatocellular carcinoma (HCC) remains unexplored." (PMID 26249031, 2015).
leiomyoma (1 paper, 2017). A well-circumscribed benign smooth muscle neoplasm characterized by the presence of spindle cells with cigar-shaped nuclei, interlacing fascicles, and a whorled pattern. "Lastly, we confirmed that levels of transcript encoding HES6 (P < 0.05), ZBTB16 (P < 0.02), ITPKA (P < 0.05), and CORIN (P < 0.05) were significantly higher in specimens of luteal phase leiomyomas than proliferative phase specimens." (PMID 28637297, 2017).
lymph node metastasis (1 paper, 2020). "In the current study, we present evidence that ITPKA is over-expressed in LUAD and the over-expression of ITPKA is associated with lymph node metastasis and more advanced T stage." (PMID 32015686, 2020).
Obesity (1 paper, 2023). Accumulation of substantial excess body fat. "PCSK9, MST1, and RPS6K1 predominantly mediated the detrimental effect of sedentary behavior on CAD, while the effect of smoking was mainly mediated by RGMB, PCSK9, ITPKA, RPS6KA1, and AGER, which partially aligned with the observed association pattern between obesity and CAD." (PMID 38049831, 2023). "The detrimental effect of obesity on CAD appears to be primarily mediated by MAP1LC3A, ANGPTL4, RPS6KA1, PCSK9, ITPKA, and AGER." (PMID 38049831, 2023).
osteoarthritis (1 paper, 2024). A noninflammatory degenerative joint disease occurring chiefly in older persons, characterized by degeneration of the articular cartilage, hypertrophy of bone at the margins and changes in the synovial membrane. "Additionally, curcumin can exert therapeutic effects on osteoarthritis by targeting the PIP4K2C, INPP5J, ITPKA, ITPKB, ISYNA1, and PLCH2 proteins associated with inositol phosphate metabolism." (PMID 37938371, 2024).
ovarian carcinoma (1 paper, 2021). A malignant neoplasm originating from the surface ovarian epithelium. "In this study, we examined the expression pattern and functions of ITPKA in ovarian cancer and investigated the underlying molecular mechanisms." (PMID 33879633, 2021). "Although several studies have shown that ITPKA is upregulated in some cancer types, our study clearly demonstrated that ITPKA is downregulated in ovarian cancer, suggesting that the expression of ITPKA in cancer is dependent on the context of the tumor." (PMID 33879633, 2021). "Taken together, the results of this study demonstrated the tumor suppressive roles of ITPKA in ovarian cancer and provided a good explanation for the oncogenic roles of miR-203." (PMID 33879633, 2021). "Overexpression of ITPKA inhibited the anchorage-independent growth of ovarian cancer cells and induced senescence." (PMID 33879633, 2021). "In this study, we found that ITPKA was downregulated in ovarian cancer samples, and the lower expression correlated with poor survival." (PMID 33879633, 2021). "The induction of senescence by IPTKA suggested that restoring the expression of ITPKA (using an inhibitor of miR-203) and treatment with an agonist of ITPKA would be promising strategies for ovarian cancer therapy." (PMID 33879633, 2021). "We next explored the molecular mechanisms through which ITPKA inhibited the tumorigenicity of ovarian cancer cells." (PMID 33879633, 2021). "Knockdown of ITPKA expression enhanced the anchorage-independent growth of ovarian cancer cells and inhibited cell senescence." (PMID 33879633, 2021). "However, knockdown of ITPKA promoted the anchorage-independent growth of ovarian cancer cells and inhibited senescence." (PMID 33879633, 2021). "In summary, ITPKA was downregulated in ovarian cancer and negatively regulated by miR-203." (PMID 33879633, 2021). "ITPKA inhibited ovarian cancer cell colony formation and tumorigenesis and induced cell senescence." (PMID 33879633, 2021). "In summary, this study has demonstrated the tumor suppressive roles of ITPKA in ovarian cancer, which suggests that activation of ITPKA might be beneficial for the treatment of ovarian cancer." (PMID 33879633, 2021). "Moreover, ITPKA was negatively regulated by miR-203, a microRNA that has been previously reported to be upregulated in ovarian cancer." (PMID 33879633, 2021). "Moreover, we have provided evidence that ITPKA possesses tumor suppressor activity in ovarian cancer cells." (PMID 33879633, 2021). "Additionally, in future studies, it is necessary to verify the effects of ITPKA on senescence using an ovarian cancer mouse model." (PMID 33879633, 2021). "IHC staining clearly showed the downregulation of ITPKA in ovarian cancer tissues." (PMID 33879633, 2021). "The expression of ITPKA was evaluated in ovarian cancer samples." (PMID 33879633, 2021). "Moreover, we explored the regulation of ITPKA by miR-203 in ovarian cancer." (PMID 33879633, 2021). "Although previous studies have shown that ITPKA is expressed in a broad range of tumor types and that ITPKA gene body methylation inhibits its expression, thus serving as a novel and potential biomarker for early cancer detection, the expression pattern of ITPKA in ovarian cancer remains unknown." (PMID 33879633, 2021). "To investigate the functions of ITPKA in ovarian cancer, we transfected the ovarian cancer cell lines OVCA429 and OVCAR3 with a vector (Flag-ITPKA) to overexpress ITPKA." (PMID 33879633, 2021).
sarcoidosis (1 paper, 2025). Sarcoidosis is a multisystemic disorder of unknown cause characterized by the formation of immune granulomas in involved organs. "Among 19 protein-sarcoidosis associations, strong genetic colocalization evidence was observed for 8 pairs, including BTN3A3, ANXA11, ITPKA, BTN3A1, G3BP1, IL1RN, IL2RB, and NFKB1." (PMID 40075078, 2025).
small cell lung carcinoma (1 paper, 2018). Small cell lung cancer (SCLC) is a highly aggressive malignant neoplasm, accounting for 10-15% of lung cancer cases, characterized byrapid growth, and early metastasis. "ITPKA is preferentially expressed in cell lines derived from metastases of small cell lung cancer and squamous lung carcinoma, whereas pulmonary adenocarcinoma shows a high expression frequency of ITPKA in primary tumor cells." (PMID 30352093, 2018).
cancer (17 papers, 2013 to 2023). A tumor composed of atypical neoplastic, often pleomorphic cells that invade other tissues. "Inositol-1,4,5-trisphosphate-3-kinase-A (ITPKA) has recently been found to be implicated in the tumor progression of various cancers." (PMID 26249031, 2015). "The expression of genes and isoforms associated with cancer stage and clinical outcome make ITPKA the potential target of advanced stage KIRC therapy." (PMID 24564989, 2013). "Meanwhile, there are a lot of reports, showing that this overexpression is associated with poor clinical outcome of cancer patients, and knock-down and overexpression approaches revealed that a high level of ITPKA increases the metastatic potential of tumor cells in vitro and in vivo." (PMID 36688944, 2023). "The mutation rate of ITPKA is low, approximately 1.1%, in pan-cancer tissue." (PMID 37664985, 2023). "Moreover, expression abundance of a number of genes and isoforms is predictive of the risk of cancer death in an independent dataset, such as gene and isoform expression of ITPKA, the expression of a functional important isoform of UPS19." (PMID 24564989, 2013). "ITPKA is reported to be a bifunctional protein that phosphorylates Ins P3 via kinase activity and cross-links f-actin via f-actin-binding activity, which accounts for the ITPKA-promoting effects on cancer development." (PMID 37056339, 2023). "Through a series of studies, Sabine’s team has found that ITPKA expression was up-regulated in a variety of cancer cells, and silencing ITPKA inhibited while overexpressing ITPKA promoted cancer cell migration in vitro and metastasis in vivo." (PMID 37664985, 2023). "Through a series of studies, Sabine’s team found that ITPKA expression was up-regulated in a variety of cancer cells, and silencing ITPKA inhibited cancer cell migration in vitro and metastasis in vivo, while overexpressing ITPKA promoted these processes." (PMID 37664985, 2023). "It is known that the roles of ACADSB, ACADM, HADH, PYCR1 and ITPKA have been explored in cancers, whereas PAFAH2 not12–16." (PMID 37460577, 2023). "The expression of ITPKA went up constantly while drug sensitivity of cancer cells to Alisertib, NTRC-0066-0, SNS-314 and CCT-271850 rose." (PMID 36685893, 2022). "In lung cancer, the methylation of ITPKA occurs in in situ carcinoma and increases with the level of invasion." (PMID 36443876, 2022). "The inositol triphosphate 3-kinase A gene (ITPKA) is a potentially oncogenic gene that is upregulated in a variety of cancers." (PMID 36443876, 2022). "Inositol-trisphosphate 3-kinase A (ITPKA) promotes the motility of cancer cells by controlling the dynamics of the cytoskeleton." (PMID 33879633, 2021). "Taken together, these results demonstrated that ITPKA inhibited the colony formation of cancer cells and induced cell senescence." (PMID 33879633, 2021). "Several recent studies reported the aberrant expression of ITPKA in malignancy disease and usually made cancer more aggressive." (PMID 32015686, 2020). "ITPKA could influence cancer cell migration, invasion, and proliferation via EMT, and interacting with DBN1." (PMID 32015686, 2020). "The expression of ITPKA in adenocarcinoma might increase the invasive potential of cancer cells." (PMID 30352093, 2018). "Mechanistically, ITPKA executed its action through the inducting of epithelial-mesenchymal transition (EMT) and interacting with Drebrin 1 (which is related to cancer metastasis)." (PMID 32015686, 2020). "Drugs targeting MST1, ITPKA, CD274 were mainly designed to treat cancers." (PMID 36857861, 2023). "The authors concluded that ITPKA body methylation, absent in non-malignant lung tissues, appears at the premalignant stage and progressively increases with cancer development, further emphasizing its potential application for early cancer detection." (PMID 30917582, 2019).